CYP19A1 (cytochrome P450 family 19 subfamily A member 1)
Description:
A cytochrome P450 monooxygenase that catalyzes the conversion of C19 androgens, androst-4-ene-3,17-dione (androstenedione) and testosterone to the C18 estrogens, estrone and estradiol, respectively. Catalyzes three successive oxidations of C19 androgens: two conventional oxidations at C19 yielding 19-hydroxy and 19-oxo/19-aldehyde derivatives, followed by a third oxidative aromatization step that involves C1-beta hydrogen abstraction combined with cleavage of the C10-C19 bond to yield a phenolic A ring and formic acid. Alternatively, the third oxidative reaction yields a 19-norsteroid and formic acid. Converts dihydrotestosterone to delta1,10-dehydro 19-nordihydrotestosterone and may play a role in homeostasis of this potent androgen. Also displays 2-hydroxylase activity toward estrone. Mechanistically, uses molecular oxygen inserting one oxygen atom into a substrate, and reducing the second into a water molecule, with two electrons provided by NADPH via cytochrome P450 reductase (CPR; NADPH-ferrihemoprotein reductase).
Synonyms: ARO1; CYAR; CYP19; ARO; P-450AROM; CPV1; aromatase; CYPXIX
Tractability: Small molecule: an approved drug acts on it; a structure with a bound ligand is known; a high-quality ligand is known; it belongs to a druggable protein family. Antibody: UniProt predicts a signal peptide or a membrane-spanning region. PROTAC: a small molecule that binds it is known.
Target class: Cytochrome P450 family 19A; Enzyme; Cytochrome P450 19A1; Cytochrome P450; Cytochrome P450 family 19
Chemical probes: LETROZOLE (high quality), PD081963, PD082397
Safety:
Unwanted effects reported when the protein is acted on. In parentheses: how it was acted on, where the effect was seen, and who reports it.
Decrease, Population growth rate (AOP-Wiki: inhibition, ovary growing follicle; AOP-Wiki: inhibition)
Reduction, Cumulative fecundity and spawning (inhibition; source: AOP-Wiki)
Decreased fertility, Reduced number of oocytes ovulated (inhibition; source: AOP-Wiki)
arthralgia (source: ClinPGx)
bone density loss (source: ClinPGx)
impaired, Fertility (source: AOP-Wiki)
irregularities, ovarian cycle (source: AOP-Wiki)
odds of vasomotor symptoms (source: ClinPGx)
odds of vasomotor symptoms (VMSs) (source: ClinPGx)
Gene: Protein-coding gene on chromosome 15 (51,208,057 to 51,338,601, reverse strand). Ensembl gene ENSG00000137869.
Subcellular location: Endoplasmic reticulum membrane; Microsome membrane
Subcellular location (Human Protein Atlas): Mitochondria
Pathways (Reactome):
Metabolism: Endogenous sterols; Estrogen biosynthesis
Disease: Defective CYP19A1 causes AEXS
Gene Ontology:
Molecular function: aromatase activity; estrogen 2-hydroxylase activity; heme binding; electron transfer activity; oxidoreductase activity, acting on paired donors, with incorporation or reduction of molecular oxygen, reduced flavin or flavoprotein as one donor, and incorporation of one atom of oxygen; oxygen binding; steroid hydroxylase activity; iron ion binding; monooxygenase activity; oxidoreductase activity, acting on paired donors, with incorporation or reduction of molecular oxygen
Biological process: androgen catabolic process; positive regulation of estradiol secretion; estrogen biosynthetic process; female gonad development; response to estradiol; steroid biosynthetic process; sterol metabolic process; androgen metabolic process
Cellular component: endoplasmic reticulum; endoplasmic reticulum membrane; membrane
Genetic constraint (gnomAD): Loss-of-function variants: 14 observed, 27.59 expected, observed/expected ratio (o/e) 0.51, 90% interval 0.33 to 0.79. The upper end of that interval is the gene's LOEUF score, 0.79, which puts it in group 3 of 6, group 1 being the genes least tolerant of losing a copy. Missense variants: 258 observed, 317.05 expected, observed/expected ratio (o/e) 0.81, 90% interval 0.73 to 0.9. Synonymous variants: 95 observed, 109.09 expected, observed/expected ratio (o/e) 0.87, 90% interval 0.74 to 1.03.
Homologues: Orthologues: chimpanzee CYP19A1 (99% identical), macaque CYP19A1 (98% identical), dog CYP19A1 (86% identical), rabbit CYP19A1 (85% identical), guinea pig CYP19A1 (81% identical), pig CYP19A1 (81% identical), mouse Cyp19a1 (79% identical), rat Cyp19a1 (77% identical), tropical clawed frog cyp19a1 (70% identical), zebrafish cyp19a1a (51% identical), Drosophila melanogaster Cyp4c3 (22% identical), Drosophila melanogaster Cyp4d2 (20% identical), and 26 more. Paralogues in human: CYP4F2 (24% identical), CYP4F11 (23% identical), CYP4F3 (23% identical), CYP4F12 (23% identical), CYP4F22 (22% identical), CYP4F8 (22% identical), CYP4B1 (21% identical), CYP4A11 (21% identical), CYP4A22 (21% identical), CYP4V2 (20% identical), CYP4X1 (20% identical), CYP4Z1 (19% identical).
Diseases named in the same sentence as CYP19A1 in open-access papers:
CYP19A1 is named in the same sentence as 169 diseases in open-access papers, as found by Europe PMC text mining. Sharing a sentence is not in itself a finding about the gene and the disease. The quoted sentences say what the papers report.
breast cancer (164 papers, 1999 to 2025). A primary or metastatic malignant neoplasm involving the breast. "Studies have shown that alteration in CYP19A1 expression is associated with adipose tissue inflammation and the development of metastasis in breast cancer." (PMID 38791004, 2024). "Kaplan–Meier survival analysis correlated gene expression levels with overall survival, associating decreased PIK3CD levels with worse prognosis in breast cancer and elevated CYP19A1 expression with poorer survival in colon cancer." (PMID 39204124, 2024). "CYP19A1 is important in the conversion of testosterone to oestrogen and SNP rs4775936 has been linked to the incidence of breast cancer." (PMID 35301404, 2022). "Studies have found that in addition to ESR1 and CYP19A1 gene mutations, 21.5% of AIs drug-resistant breast cancer patients have abnormal amplification of CYP19A1 gene." (PMID 35657638, 2022). "For instance, the transcription of CYP19A1 (a gene encoding the aromatase enzyme) was downregulated in MDA-MB-231 breast cancer cells expressing aromatase following the inhibition of SIRT1 by treatment with both cambinol and inhibitor VII." (PMID 36291902, 2022). "Changes in CYP19A1 gene expression levels have been associated with increased risk and increased aggressiveness of breast cancer." (PMID 34133482, 2021). "Only the protein encoded by CYP19A1 (aromatase) is targeted by clinically approved drugs, with indications for breast cancer and Cushing syndrome." (PMID 34675350, 2021). "At the same time, germline single nucleotide polymorphisms (SNPs) in CYP19A1 have been associated with variation in circulating estrogen concentrations and with breast cancer risk." (PMID 32701512, 2020). "The gene CYP19A1 with the variant rs10046 has previously been reported to be associated with estradiol levels and postmenopausal breast cancer in European population." (PMID 32894086, 2020). "Recently, it has been reported that increased expression level of CYP19A1 mRNA in peripheral blood has been shown to be associated with locoregional relapse of breast cancer." (PMID 33716953, 2020). "The CYP19A1 SNP rs7176005 was significantly associated with breast cancer for both the Rare Hz (TT) vs Het (CT) (χ2 = 4.57) and the Rare Hz (TT) vs Common Hz (CC) (χ2 = 8.44) genetic models." (PMID 31477036, 2019). "Genes MIR124-2, PBX1, SKI, GHSR and RBPMS were reported to be associated with breast cancer, and a gene CYP19A1 was reported to be be associated with endometrial cancer." (PMID 31640538, 2019). "Aberrant expression or hyperactivation of aromatase (CYP19A1)-estrogen receptor (ESR) axis is well identified as one of the major causes of breast cancer." (PMID 31741086, 2019). "Genetic variants in CYP19A1, the gene encoding aromatase, have been reported to be associated with circulating estrogen concentrations, a key risk factor for breast cancer." (PMID 29363090, 2018). "Here we analyzed the expression of intra-tumoral CYP19A1 messenger RNA (mRNA) and the genotypes of rs10046, a well-characterized single nucleotide polymorphism in CYP19A1, in 138 breast cancer patients and 15 breast cancer cell lines." (PMID 29363090, 2018). "Associations of CYP19A1 expression with well-established clinical and histopathological characteristics of breast cancer were visualized with boxplots." (PMID 29363090, 2018). "Among other CYP19A1 variants, the rs10046 SNP has been associated with increased levels of circulating estrogen and an increased breast cancer risk in some studies." (PMID 29363090, 2018). "The potential association of CYP19A1 variants with breast cancer prognosis has also been investigated in detail." (PMID 29363090, 2018). "The identification of CYP19A1 variants that associate with breast cancer patient outcome would provide a strong rationale for AI treatment of endometrial cancer patients carrying these variants." (PMID 28487654, 2017).
breast cancer (continued). "Previous studies have mainly focused on the relationship between polymorphisms in the CYP19A1 gene and breast cancer." (PMID 29228596, 2017). "Given the racial/ethnic disparities in breast cancer, we evaluated the association between CYP19A1 single nucleotide polymorphisms (SNPs) on disease progression in women with breast cancer from different racial/ethnic backgrounds." (PMID 27994616, 2016). "Only a few studies have investigated the association between polymorphisms in Cytochrome P450 (CYP) CYP19A1 (aromatase) and disease-free survival in breast cancer." (PMID 27029552, 2016). "Analysis of the different clinical characteristics and outcomes according to rs4646 and rs12592697 polymorphisms in the CYP19A1 in premenopausal women with breast cancer." (PMID 27994616, 2016). "Two SNPs in CYP19A1 were associated with disease outcomes particularly in the cohort of postmenopausal women diagnosed with breast cancer at our institution." (PMID 27994616, 2016). "A recent review and meta-analysis analyzed the influence of common CYP19A1 polymorphisms on postmenopausal patients with breast cancer treated with AIs, indicating a certain heterogeneity between studies." (PMID 27825388, 2016). "Analysis of the different clinical characteristics and outcomes according to rs4646 and rs12592697 polymorphisms in the CYP19A1 in postmenopausal women with breast cancer." (PMID 27994616, 2016). "We compared the genotypic and allelic frequencies of 11 SNPs in estrogen biosynthesis genes based on the case-control study and observed that rs700519 in CYP19A1 was significantly associated with breast cancer risk." (PMID 25689428, 2015). "Previous studies have reported that CYP19A1 polymorphisms are related to breast cancer risk in healthy women, and several CYP19A1 gene variants are associated with a lower cancer risk." (PMID 24065098, 2013). "The associations in breast cancer survived correction for multiple testing of 15 genes (pglobal corrected = 0.045 for CYP19A1 and 0.03 for UGT2B4)." (PMID 20617168, 2010). "CYP19A1 rs10046 has previously been reported to influence levels of estradiol and possibility impact on breast cancer risk." (PMID 17615053, 2007). "The CYP19A1 gene, encoding for the aromatase enzyme, can also be mutated in breast cancer cells." (PMID 38567308, 2024). "Interestingly, CYP19A1 antagonists have previously been found to reduce dementia risk in women with breast cancer, but CYP19A1 has reported neuroprotective roles as well." (PMID 38550989, 2024). "Docking studies and molecular dynamics simulations indicated that these three isoflavones, generated via biotransformation, are potent inhibitors of the target protein aromatase (CYP19A1); consequently, they can be used to prevent breast cancer risk in postmenopausal women." (PMID 35625301, 2022). "CYP19A1 genetic variants in relation to breast cancer survival in a large cohort of patients." (PMID 35563727, 2022). "Some authors have described a significant association between the levels of gene expression of CYP19A1 and breast cancer, however there is a need for further elucidation of the association between these levels and increased risk of breast cancer, survival, and disease progression." (PMID 34133482, 2021). "In addition, elevated levels of CYP19A1 mRNA were significantly associated with local recurrence and incidence of metastases, as well as death related to breast cancer." (PMID 34133482, 2021). "CYP19A1 (Cytochrome P450 family 19 sub-familyA1) gene plays an important role in the biosynthesis of estrogen and it has been associated with the progression of breast cancer in the Chinese population." (PMID 32487238, 2020). "The CYP19A1 gene, which encodes the enzyme responsible for androgen aromatization into estrogens, may play an important role in breast cancer aggressiveness." (PMID 32460723, 2020).
breast cancer (continued). "We suggest that the variants alleles of CYP19A1 SNPs; rs7176005 and rs6493497 could be an influence factors for increasing the breast cancer risk." (PMID 31477036, 2019). "Moreover, we wanted to investigate the association of CYP19A1 expression with widely used clinical and histopathological characteristics of breast cancer, in particular the ER status and the age at onset." (PMID 29363090, 2018). "Moreover, higher CYP19A1 mRNA levels were significantly associated with the incidence of metastasis and local recurrence as well as breast cancer-related death." (PMID 29363090, 2018). "Since elevated levels of circulating estrogen increase the risk of breast cancer and other hormone-dependent cancers, it seems plausible that CYP19A1 variants associated with elevated estrogen levels should also be associated with an increased risk of these cancers." (PMID 29363090, 2018). "One study recently reported similar associations in postmenopausal patients with breast cancer enrolled in the TEAM trial: CYP19A1 variants linked with lower estrogen levels were associated with increased risk of early vasomotor and musculoskeletal symptoms under exemestane." (PMID 27825388, 2016). "In the present study, there was a significant interaction between CYP1A2 rs762551 and CYP19A1 rs4646 with a high risk for breast cancer events, especially within five years, among patients with any C-allele of CYP1A2 rs762551 and C/C-carriers of CYP19A1 rs4646." (PMID 27029552, 2016). "Moreover, tamoxifen induced CYP19A1 gene expression and estrogen production in breast cancer-associated fibroblasts." (PMID 26828520, 2016). "Thus, there is biological plausibility in the association between CYP19A1 polymorphisms and postmenopausal breast cancer." (PMID 20617168, 2010). "Polymorphisms in CYP19A1 have been related to the pathogenesis of breast cancer (BC)." (PMID 20144226, 2010). "CYP19A1 encodes for the aromatase enzyme, which plays an essential role in estrogen biosynthesis by chemically aromatizing androgens to estrogen (this conversion is tightly regulated, and any dysfunction is related to a range of disorders—breast cancer and polycystic ovary syndrome, to name a few)." (PMID 36551837, 2022). "Since genetic polymorphisms in the CYP450 genes vary according to race/ethnicity, it is possible that polymorphisms in CYP19A1 may, in part, account for the racial/ethnic differences in the risk and disease behavior of hormone-related diseases such as breast cancer." (PMID 27994616, 2016). "This translational study within the TEXT trial for premenopausal patients with hormone-receptor-positive early breast cancer provides evidence that the CYP19A1 rs10046 polymorphism may influence endocrine treatment side effects under combined endocrine therapy." (PMID 27825388, 2016). "We hypothesize that certain polymorphisms in CYP19A1 are associated with racial/ethnic differences in allele frequencies resulting in differences in the risk of disease progression and stage at presentation among women with breast cancer." (PMID 27994616, 2016). "Thus, we hypothesized that the allele frequency distributions in CYP19A1, because of its association with breast cancer and role in estrogen biosynthesis, may be different between populations of African and European ancestry from Arkansas." (PMID 25647083, 2015). "Specifically, ATZ’s stimulatory effect on breast cancer is mediated, at least partially, through enhanced CYP19A1 activity, the key enzyme converting testosterone to estradiol." (PMID 40771272, 2025). "For example, by inducing ER stress in estrogen receptor-positive breast cancer cells, ionizing radiation downregulates CYP19A1 expression and reduces estradiol synthesis, which ultimately inhibits cell proliferation." (PMID 41050076, 2025). "While IL-6 treatment leads to aromatase activation in endometrial and breast cancers, in dermal fibroblasts, IL-6 and E2 increased CYP19A1 transcript levels, suggesting increased aromatase activation." (PMID 39000334, 2024).